ETFRF1 (electron transfer flavoprotein regulatory factor 1)
Description:
Acts as a regulator of the electron transfer flavoprotein by promoting the removal of flavin from the ETF holoenzyme (composed of ETFA and ETFB).
Synonyms: LYRM5
Tractability: PROTAC: ubiquitination databases record sites on it.
Gene: Protein-coding gene on chromosome 12 (25,194,775 to 25,209,645, forward strand). Ensembl gene ENSG00000205707.
Subcellular location: Mitochondrion
Gene Ontology:
Molecular function: enzyme inhibitor activity; protein binding
Biological process: negative regulation of oxidative phosphorylation; negative regulation of cellular respiration
Cellular component: mitochondrion
Genetic constraint (gnomAD): Loss-of-function variants: 9 observed, 7.36 expected, observed/expected ratio (o/e) 1.22, 90% interval 0.73 to 1.86. That is too few expected variants to judge how well the gene tolerates losing a copy. Missense variants: 82 observed, 84.22 expected, observed/expected ratio (o/e) 0.97, 90% interval 0.81 to 1.17. Synonymous variants: 29 observed, 27.77 expected, observed/expected ratio (o/e) 1.04, 90% interval 0.78 to 1.42.
Homologues: Orthologues: chimpanzee ETFRF1 (100% identical), macaque ETFRF1 (100% identical), dog ETFRF1 (93% identical), pig ETFRF1 (92% identical), rabbit ETFRF1 (90% identical), rat Etfrf1 (88% identical), mouse Etfrf1 (87% identical), guinea pig ETFRF1 (86% identical), tropical clawed frog etfrf1 (74% identical), zebrafish lyrm5a (66% identical), Caenorhabditis elegans Y42A5A.5 (52% identical), Drosophila melanogaster osi (46% identical).
Diseases named in the same sentence as ETFRF1 in open-access papers:
ETFRF1 is named in the same sentence as 1 disease in open-access papers, as found by Europe PMC text mining. Sharing a sentence is not in itself a finding about the gene and the disease. The quoted sentences say what the papers report.
malnutrition (1 paper, 2024). Inadequate nutrition resulting from poor diet, malabsorption, or abnormal nutrient distribution. "ETFRF1 was also listed among the genes that were dysregulated in subcutaneous and perirenal adipose tissue of sheep as a resultant of pre- and early postnatal malnutrition." (PMID 38474355, 2024).